Y_RNA (Y RNA )
Gene: Miscellaneous RNA gene on chromosome 1 (184,171,714 to 184,171,823, reverse strand). Ensembl gene ENSG00000199840.
Homologues: Orthologues: chimpanzee Y_RNA (100% identical), macaque Y_RNA (98% identical). Paralogues in human: Y_RNA (89% identical), RNY1 (88% identical), Y_RNA (87% identical), Y_RNA (86% identical), Y_RNA (85% identical), RNY1P11 (85% identical), Y_RNA (84% identical), RNY1P10 (83% identical), RNY1P8 (83% identical), Y_RNA (83% identical), RNY1P13 (82% identical), Y_RNA (82% identical), and 98 more.